TTC21B (tetratricopeptide repeat domain 21B)
Diseases named in the same sentence as TTC21B in open-access papers (continued):
Sharing a sentence is not in itself a finding about the gene and the disease.
cardiomyopathy (1 paper, 2018). A disease of the heart muscle or myocardium proper. "Among them are also cytoskeletal regulators, that when mutated cause FSGS or cardiomyopathy (e.g. actinin-4, TTC21B and myosin-7)." (PMID 29768408, 2018).
Hepatic fibrosis (1 paper, 2023). The presence of excessive fibrous connective tissue in the liver. "Homozygous NPHP1 possibly modified by heterozygous NPHP4 with early-onset ESKD;Compound heterozygous NPHP3 modified by heterozygous NPHP4 variant with early-onset ESKD and hepatic fibrosis;TTC21B contributes possible modifier alleles to NPHP4." (PMID 37628633, 2023).
Hydrocephalus (1 paper, 2023). Hydrocephalus is an active distension of the ventricular system of the brain resulting from inadequate passage of CSF from its point of production within the cerebral ventricles to its point of absorption into the systemic circulation. "For example, defaults in centrosomal protein Cep290 or intraflagellar transport (IFT) components such as Kinesin family member 3a (Kif3a), Ift188 and Ttc21b, impair primary cilia formation/signaling in turn disrupting ependymal cilia and leading to hydrocephalus in mice." (PMID 36859317, 2023).
spina bifida aperta (1 paper, 2019). "These alleles affect ciliary localization of GPR63 in vitro and genetically interact with Ttc21baln/aln as Gpr63;Ttc21b double mutants show unique phenotypes including spina bifida aperta and earlier embryonic lethality." (PMID 31730647, 2019).
cancer (3 papers, 2018 to 2025). A tumor composed of atypical neoplastic, often pleomorphic cells that invade other tissues. "Moreover, nonsense mutations were detected in GRHL2, GRIN1, NOL9 and TTC21B, however only GRHL2 and GRIN1 were previously shown to be involved in cancer." (PMID 29854292, 2018). "These modules contained several cancer regulators such as Intraflagellar Transport (IFT) complex proteins (IFT74, IFT88), BBSome complex proteins (BBS2, BBS7, BBS9, BBS12), exocyst complex components (EXOC3, EXOC4, EXOC6B, EXOC7, and EXOC8), TTC8, TTC21B, EVC, and NEK1." (PMID 40700427, 2025).
genetic disease (2 papers, 2025). "Currently, there is no cure for genetic diseases caused by single-gene mutations such as TTC21B." (PMID 41378128, 2025).
TTC21B also shares sentences with these, for which no sentence is quoted: kidney disease (5 papers); cystic kidneys (4); diabetes (2); End Stage Renal Disease (2); fatty liver disease (2); kidney failure (2); Nephropathy (2); Alport syndrome (1); autosomal dominant polycystic kidney disease (1); Biliary Cirrhosis (1); cerebral aneurysm (1); cleft palate (1); collagenopathies (1); focal epilepsy (1); genetic generalized epilepsy (1); Glucose intolerance (1); Hepatic cysts (1); Hyperoxaluria (1); Insulin resistance (1); liver failure (1); Lowe syndrome (1); Meckel-Gruber syndrome (1); membranoproliferative glomerulonephritis (1); metabolic disease (1); metabolic syndrome (1); Methylmalonic aciduria (1); Nephrotic range proteinuria (1); Onset (1); primary ciliary dyskinesia (1); renal failure (1).
A further 5 diseases each share a sentence with TTC21B in 1 paper.